INS (insulin)
Diseases named in the same sentence as INS in open-access papers (continued):
Sharing a sentence is not in itself a finding about the gene and the disease.
Insulin resistance (continued). "Adiponectin promotes insulin sensitivity, whereas adiponectin deficiency exacerbates insulin resistance and AD neuropathology." (PMID 31718027, 2019). "Type 2 diabetes (T2D) is known as a disease caused by gene alterations characterized by insulin resistance, thus the insulin-responsive tissues are of great interest for T2D study." (PMID 30972105, 2019). "Loss of systemic insulin sensitivity is an important feature of the metabolic syndrome, and obesity-related insulin resistance of skeletal muscle and the liver has been studied intensively." (PMID 31195596, 2019). "In several studies of populations with CKD, insulin resistance was associated with a more rapid decline in kidney function compared to those who were insulin sensitive." (PMID 30786864, 2019). "The administration of betanin for 20 days was able to regulate glucose and insulin levels and reverse insulin resistance, even under the concomitant deleterious stimulus caused by the high-fat feed." (PMID 31443409, 2019). "First, we review the role and molecular mechanism of insulin-mediated glycometabolism and the associated abnormalities observed in insulin resistance." (PMID 31649547, 2019). "It is also known to enhance the action of insulin and insulin resistance has been associated with Cr deficiency." (PMID 30811496, 2019). "On the other hand, neuronal metabolic impairment caused by blunted or deficient insulin signaling, called insulin resistance, affects neuronal functions and has been suggested to parallel the onset and progression of AD pathology." (PMID 29736736, 2019). "Third, Sirt6 deficiency resulted in impaired insulin signaling and increased apoptosis under ER stress, whereas Sirt6 overexpression and Sirt6 activation improved hepatic insulin resistance and apoptosis." (PMID 31541078, 2019). "Two miRNA modules (red and blue) identified in the H-CLA group were enriched for GO terms associated with insulin signaling pathway and insulin resistance." (PMID 31354792, 2019). "Genetic AS160 deficiency in humans is associated with insulin resistance based on glucose and insulin values from an OGTT." (PMID 31034517, 2019). "Insulin resistance is the primary cause of type 2 DM and refers to individuals whose target cells lose their sensitivity to insulin." (PMID 30945455, 2019). "Insulin resistance is a metabolic defect primarily associated with resistance to insulin-mediated glucose disposal." (PMID 31569751, 2019). "This was associated with increased insulin sensitivity and improved glucose uptake, thereby reducing insulin resistance." (PMID 31878222, 2019). "Epigenetic programming of insulin resistance in human studies was reported to be involved in the epigenetic modifying enzyme, inflammatory/proinflammatory factors, insulin associated signaling, energy balance regulation, and microRNA." (PMID 31849831, 2019). "Integrins are important regulators of insulin action and represent novel therapeutic targets to treat the underlying insulin resistance associated with T2D (Williams, Kang & Wasserman, 2015)." (PMID 31380149, 2019). "Mice fed HFD with 0.2% TMAO had higher fasting insulin level and homeostasis model assessment-estimated insulin resistance and impaired glucose tolerance associated with the hepatic insulin signaling pathway and adipose tissue inflammation." (PMID 31275408, 2019). "To discuss the potential common mechanisms underlying MetS and skin diseases, we focus on insulin signaling and insulin resistance, as well as chronic inflammation including adipokines and proinflammatory cytokines related to molecular mechanisms." (PMID 31824416, 2019). "DM type 1 is characterized by a loss of insulin-producing β-cells due to autoimmune destruction or dysfunction, whereas type 2 is triggered by insulin resistance and lower insulin secretion." (PMID 30930950, 2019).
Insulin resistance (continued). "For example, in IRS-1-deficient mice, insulin resistance develops mainly due to decreased insulin-stimulated glucose metabolism in the muscle alone." (PMID 30717446, 2019). "This is associated with the inhibition of skeletal muscle cells insulin signaling and subsequently the development of muscle insulin resistance." (PMID 30669379, 2019). "Gestational Diabetes Mellitus (GDM) is considered as an early marker of glucose intolerance, associated with both insulin resistance and impaired insulin secretion and an increased risk of maternal and fetal complications during pregnancy." (PMID 31448279, 2019). "Insulin resistance is caused by impaired insulin signaling, and β cells promote abnormal production of insulin to maintain glucose homeostasis." (PMID 31541119, 2019). "Insulin resistance is an important metabolic hallmark of acromegaly caused mainly by the insulin-antagonizing effects of GH in general and the lipolytic effects of GH in particular." (PMID 31417493, 2019). "In contrast to these studies, a trial conducted on patients with T2D and CHD, however, showed decreasing level of insulin associated with improving insulin resistance/sensitivity indices." (PMID 32802105, 2019). "Obesity is well-established as a predisposing factor for the appearance of hepatic steatosis, NAFLD being strongly associated with both hepatic and peripheral insulin resistance with a defect in the ability of insulin to suppress endogenous glucose production." (PMID 31417486, 2019). "At baseline, ATX levels were positively associated with BMI, fat mass, insulin, insulin resistance (HOMA‐IR), and leptin and negatively with fat‐free mass." (PMID 30821134, 2019). "Due to the primary site of insulin clearance, liver is associated with the development of insulin resistance." (PMID 31861309, 2019). "Because of the association between AD and diabetes, studies were undertaken on the effect of dysfunctional insulin signaling in AD progress, which led to subsequent studies that showed brain insulin resistance is a hallmark of AD." (PMID 31275224, 2019). "Biomarkers measuring cancer risk were measured with fasting blood draw including insulin resistance (fasting plasma insulin and glucose levels), systemic inflammation (levels of CRP), and oxidative stress measured from urine samples." (PMID 30760246, 2019). "Remarkably, an increase in visceral adipose tissue Tregs has been proposed as the adipo-immune driver of age-associated insulin resistance, as Treg depletion in adipose tissue increased insulin sensitivity." (PMID 31443389, 2019). "Garlic improves insulin sensitivity and the associated metabolic syndrome in animal models, and its derivatives reduce both insulin resistance and blood glucose in streptozotocin-induced and alloxan-induced DM mellitus in rats and mice." (PMID 31336965, 2019). "From the KEGG pathway analysis in the current study, the glucagon signalling pathway, insulin resistance and insulin signalling pathway were found to be significantly associated with the DEGs between the two pig breeds." (PMID 31501489, 2019). "A dietary pattern that is associated with elevated insulin has been identified with increasing risk of hyperglycemia, metabolic syndrome and insulin resistance, particularly in an overweight/obese population." (PMID 31035472, 2019). "Accordingly, 12-month-old transgenic mice that overexpress a GHR antagonist exhibited improved insulin sensitivity and learning, whereas overexpressed GH caused insulin resistance and impaired memory retention." (PMID 31939479, 2019). "It is generally thought that its pathogenesis is linked to insulin resistance, insulin secretion defects, obesity, inflammation and other factors." (PMID 31949438, 2019). "ROS are probably involved in the onset of inflammation in pancreatic islets, and pancreatic cell death inevitably implies a loss of insulin secretion by β-cells, which in turn promotes insulin resistance." (PMID 31487953, 2019).
Insulin resistance (continued). "It is well known that uremic state is associated with insulin resistance and a clear relationship between insulin release, glucose metabolism, ARP-release (ARPr) and pro-inflammatory cytokines has been established." (PMID 31191339, 2019). "As an organ of an insulin-responsive target, the loss of muscle mass contributed to insulin resistance, MetS and HTN." (PMID 30964893, 2019). "Insulin resistance (IR) is associated with an impaired biological response to insulin stimulation of key target tissues, particularly liver, muscle, and adipose tissue." (PMID 30889804, 2019). "In T2D, the underlying mechanism includes insufficient insulin secretion from pancreatic β-cells and insulin resistance." (PMID 30759846, 2019). "In suckling piglets, IUGR increased serum glucose and insulin levels, indicating an increased risk of insulin resistance." (PMID 31847151, 2019). "The well-known cause of diabetes in a majority of cases in Asia is reduced insulin secretion; whereas that for the United States and Europe is insulin resistance." (PMID 31661025, 2019). "These factors can cause insulin resistance and lead to hyperglycemia, which has a further effect in reducing insulin secretion via “glucose toxicity”." (PMID 30873113, 2019). "Looking at the role of IgG subclasses in T2DM, total IgG2 has been associated with insulin-resistance in mouse skeletal muscle through activation of epithelial FcγRIIb, an inhibitory Fc-receptor, and the impairment of insulin epithelial translocation." (PMID 31921122, 2019). "Insulin resistance (IR) identifies a disorder in which a given concentration of insulin is associated with a subnormal glucose response." (PMID 31749765, 2019). "In normal-weight subjects, a high level of interleukin 6 is associated with insulin sensitivity, although as fat mass increases, interleukin 6 contributes to insulin resistance." (PMID 30457109, 2019). "Most likely in theory, insulin resistance is associated with an inflammatory response and in turn, either the insulin resistant or inflammation or both, contribute to cognitive decline." (PMID 31440156, 2019). "Hepatic insulin resistance is caused by interrupting insulin-induced suppression of hepatic glucose production but raising preserved stimulation of lipogenesis conversely." (PMID 30642126, 2019). "Genetically predicted insulin and insulin resistance are consistently positively associated with higher risk of IHD16–18, independent of adiposity." (PMID 31508506, 2019). "Fatty tissue content in the pancreas is linked to reduced insulin resistance and suppressed insulin secretion." (PMID 31652553, 2019). "It is well established that cortisol excess causes insulin resistance in man, which in turn impairs the ability of insulin to suppress glucose production and glucose utilization resulted from glucocorticoid excess." (PMID 31396037, 2019). "IL-6 can also certainly avert insulin synthesis, and excess IL-6 leads to severe pancreatic islet cytotoxicity and cause insulin resistance." (PMID 31337059, 2019). "Because insulin signalling has a central role in ovarian functions, insulin resistance associated with high calorie diet ingestion can negatively alter the ovarian steroidogenesis, follicular development, and granulosa cell proliferation in female." (PMID 31089371, 2019). "Epigenetic programming of insulin resistance was disclosed in more details involved in DNA or histone-modifying enzyme, adipocytokines, insulin associated signaling, lipid metabolism, microRNA, and so on." (PMID 31849831, 2019). "This will activate the MAPKs, such as JNK, thereby inhibiting the insulin signaling transduction and causing hepatic insulin resistance." (PMID 32082162, 2019). "This is biologically plausible because insulin resistance and high levels of insulin cause increased sympathetic activity and abnormal tubular sodium absorption, which eventually lead to endothelial cell damage and thus increased risk of pre-eclampsia." (PMID 31554279, 2019).
Insulin resistance (continued). "In T1DM and T2DM, respectively, insufficient insulin production or insulin resistance causes a significant reduction of glucose uptake." (PMID 31572181, 2019). "In terms of study limitations, the STZ model chosen reflects insulin deficient hyperglycemia while the majority of patients potentially in need of cell therapy are type 2 diabetics with both hyperglycemia and insulin resistance." (PMID 31534514, 2019). "Recent studies provide evidence that regular physical activity lowers the risk of insulin resistance and improves insulin sensitivity when individuals comply with physical activity guidelines." (PMID 31888175, 2019). "PWDS have a heightened cardiometabolic risk profile and high oxidative stress associated with elevated insulin resistance, poor insulin sensitivity, atherosclerosis and hypertension." (PMID 31745461, 2019). "Lipid metabolites, such as TG and TC, directly antagonize insulin signaling and are considered the main cause of insulin resistance." (PMID 31013790, 2019). "The ability of iron to induce insulin resistance was maintained in autophagy deficient cells, and a slightly enhanced effect was observed in response to 100 nM insulin." (PMID 30874600, 2019). "Insulin resistance levels are important and should be highlighted because insulin resistenace has been shown to be an independent risk factor for cardiovascular events." (PMID 31881945, 2019). "High carbohydrate intake was associated with elevated blood glucose and insulin levels, which can promote glucose intolerance, insulin resistance and hyperinsulinemia." (PMID 31831005, 2019). "Type 2 diabetes is a common metabolic disorder related to insulin resistance, or deficiency of insulin secretion, caused by decreased insulin sensitivity and destruction of islet structure and function." (PMID 32010641, 2019). "We learned the impact of testosterone deficiency on the development of visceral obesity and insulin resistance in men, and a recent study revealed a potential mechanism, involving extranuclear actions of the androgen receptor in regulating insulin secretion." (PMID 31589598, 2019). "If insulin resistance occurs, the feedback signal from tissues causes the β-cells to increase insulin output to maintain normal glucose tolerance." (PMID 30678216, 2019). "The fasting insulin level, a marker of insulin resistance, was reported to be associated with the overall endometrial cancer risk in a Canadian population-based case-control study." (PMID 31284691, 2019). "Metformin combined with insulin targets two pathogenic aspects, insulin resistance and secretion defects in T2DM." (PMID 31038562, 2019). "It is supposed that body’s sensitivity to insulin is enhanced by vitamin D, which in turn minimizes the risk of insulin resistance that is often the precursor to diabetes type 2." (PMID 30786876, 2019). "In this context, many studies linking obesity with reductions in insulin signaling have indicated that diminished mitochondrial function/content is the initial homeostatic alteration associated with the development of insulin resistance in skeletal muscle." (PMID 30935113, 2019). "Improvement in insulin resistance through weight loss or use of sensitizing insulin drugs leads to decrease in hyperandrogenemia." (PMID 31477085, 2019). "At equal energy intake, lean seafood reduces fasting and postprandial risk markers of insulin resistance, and improves insulin sensitivity in insulin-resistant adults." (PMID 30728086, 2019). "The clinical symptoms of T2DM are hyperglycemia, insulin resistance, hyperlipidemia, and a relative deficiency of insulin secretion because of pancreatic β-cell dysfunction." (PMID 31340585, 2019). "Fatty acids can promote the activation of PKC to impair insulin signal pathway, subsequently causing hepatic insulin resistance." (PMID 31649547, 2019).
Insulin resistance (continued). "A high-fat diet (HFD) is a risk factor of systemic and muscular insulin resistance, hyperinsulinemia, and fat accumulation in insulin target organs." (PMID 30621321, 2019). "While the causes of T2DM include insulin resistance and impaired insulin secretion, some clinical evidence has shown progressive insulin secretion impairment over time in patients with T2DM." (PMID 31756973, 2019). "Adipose tissue-derived pro-inflammatory cytokines such as TNF-α and IL-6 can cause insulin resistance in adipose tissue, liver, and skeletal muscle by impairing insulin action." (PMID 31075962, 2019). "Hyperinsulinemia with insulin resistance, which causes increased levels of insulin in circulation, has been linked to breast cancer." (PMID 31292496, 2019). "In conclusion, mitochondrial dysfunction gives rise to hepatic fatty acid accumulation, which ultimately impairs insulin signal pathway and causes hepatic insulin resistance." (PMID 31649547, 2019). "It was previously suggested that fetuin-A is involved in insulin resistance by inhibiting the phosphorylation of tyrosine kinase of the insulin receptor and therefore causes a disturbance of insulin signaling." (PMID 31579450, 2019). "Decreased AMPK activity is associated with insulin resistance while AMPK activation increases insulin sensitivity." (PMID 31591391, 2019). "The upregulated Alox15 in the adipose impaired insulin signaling, but the whole-body and adipose-specific deficiency of Alox15 attenuated hyperglycemia and insulin resistance in mice." (PMID 31579613, 2019). "Given the association of serum neopterin concentration, insulin resistance, and β-cell function, such as insulin secretion, we explored the serum neopterin concentration as a predictor of the progression to T2D." (PMID 30873113, 2019). "Inhibition of mTORC1 increases insulin sensitivity, while inhibition of mTORC2 causes insulin resistance in mice." (PMID 31406105, 2019). "In several studies in rodents, the omega-3 fatty acids DHA and eicosapentaenoic acid (EPA), have been shown to facilitate formation of insulin sensitizing adipokines such as adiponectin and reduce adipokines associated with insulin resistance." (PMID 31783739, 2019). "Hyperinsulinemia to counter insulin resistance is caused by both enhanced insulin secretion and decreased insulin clearance." (PMID 30846785, 2019). "This overstimulation of ADRB2 is found to be associated with the pathogenesis of insulin resistance as it inhibits the insulin-induced translocation of GLUT4 and reduces glucose uptake via the cAMP-dependent protein kinase A-dependent pathways." (PMID 31007954, 2019). "Adipose tissue has been reported to produce pro-inflammatory cytokines, particularly TNF-α, which can impair insulin signaling, thereby increasing the risk of insulin resistance." (PMID 30249283, 2018). "It is, therefore, just as plausible that gradual elevation of insulin secretion due to hysteretic effects of glucose on beta-cell function causes age-related insulin resistance." (PMID 29892261, 2018). "Emerging studies have shown that loss of inflammatory mediators prevents insulin resistance, therefore pharmacological targeting of inflammatory pathways improve insulin action." (PMID 29950970, 2018). "The hallmark of GDM is increased insulin resistance accompanied by decreased compensatory insulin secretory response." (PMID 30089489, 2018). "The central etiological cause of MetS is commonly considered to be insulin resistance, which is defined as the failure of insulin to stimulate glucose transport to its target cells." (PMID 33266617, 2018). "Our findings are in agreement with results of recent investigations where higher insulin levels and the presence of insulin resistance were adversely associated with carotid wall thickness among children and adolescents." (PMID 30470212, 2018).